PPARD (peroxisome proliferator activated receptor delta)
Diseases named in the same sentence as PPARD in open-access papers (continued):
Sharing a sentence is not in itself a finding about the gene and the disease.
cancer (continued). "PPARD accelerated cancer proliferation by promoting the transcription and phosphorylation of AKT." (PMID 39922804, 2025). "PPARδ (also known as PPARβ) plays a multifaceted role in cancer." (PMID 39292167, 2024). "The modulation of CTL cytotoxicity by PPARδ presents a new opportunity for cancer immunotherapy." (PMID 39292167, 2024). "Furthermore, various pieces of evidence indicate that cancer cells up-regulated PPARδ, which can be used as a defense mechanism against nutritional deprivation and energy stress to improve its survival rate and promote cancer progression." (PMID 37213709, 2023). "PPARδ is upregulated in major human cancers, including pancreatic cancers." (PMID 35562376, 2022). "In our GC mouse model, PPARD overexpression induced this cancer." (PMID 35163565, 2022). "Interestingly, PPARδ expression (which is known to support cancer growth and proliferation) was decreased in response to NSAID treatment in both cell lines." (PMID 35409177, 2022). "The anticancer properties of SR13904 show that blocking PPARδ-mediated transactivation could reduce carcinogenesis, and that blockage of PPARδ could be a promising cancer therapy or prevention method." (PMID 35631448, 2022). "Moreover, deregulation of PML bodies leads to the activation of PPARδ mediated fatty acid oxidation pathways, which help in cancer stem cell maintenance, leading to disease progression and therapeutic refractoriness." (PMID 36142544, 2022). "PPARδ also emerges as a Wnt downstream target gene in the progression of several types of cancer." (PMID 33673357, 2021). "It is speculated that increased PPARδ activity may contribute to reprogramming of glutamine metabolism and drug resistance in cancer cells." (PMID 33808242, 2021). "Moreover, off-target safety concerns were present, including activation of peroxisome proliferator-activated receptor-delta (PPAR-δ), a transcription factor which plays roles in inflammation and certain cancers." (PMID 34093449, 2021). "Thus, the role of PPARδ in cancer is probably dependent on the cell type, differentiation stage, cellular context and the microenvironment of soluble mediators (e." (PMID 34921177, 2021). "It was hypothesized that PPARδ has a dual regulatory role in the angiogenesis of different carcinomas." (PMID 34712608, 2021). "In addition to PPARγ, the other PPAR subtypes PPARα and PPARδ have been also reported to play important roles in regulating cancer cell growth." (PMID 33266062, 2020). "Thus, the exact role of PPARδ agonists in cancer development appears to depend on the properties and doses of the ligands tested." (PMID 29212212, 2017). "The role of PPARδ in cancer biology appears to be context-dependent." (PMID 27270614, 2016). "Few studies have evaluated the relationship of PPARδ with malignant tumors." (PMID 25734181, 2015). "Peroxisome proliferator-activated receptor beta/delta (PPARD) is a crucial and multifaceted determinant of diverse biological functions including lipid metabolism, embryonic development, inflammatory response, wound healing and cancer." (PMID 24058710, 2013). "The involvement of PPARδ in cancer promotion in various organs is clear; however, there is controversy about whether ligand activation of PPARδ is pro- or anti-tumourigenic." (PMID 22550474, 2012). "PPARδ has been shown to regulate the proliferation and/or maturation of several cell types, including mouse embryonic stem cells, oligodendrocytes, keratinocytes, endothelial progenitors and cancer cells." (PMID 22040534, 2011). "Moreover, PPARδ is an important regulator of the proliferation of several cancer cell types (older references are reviewed by Peters and Gonzalez)." (PMID 22040534, 2011). "Takentogether, the role of PPARδ in cancer biologyremains unclear." (PMID 18551185, 2008). "The contrast indata that were reviewed here on the potential role of PPARδ in cancer, withcolon cancer being most extensively evaluated, could not be starker." (PMID 18528523, 2008).
cancer (continued). "This would be consistent with the fact that in processes, such aswound healing, inflammation, and cancer, PPARδ levels seem to increase concomitantly withupregulation of cyclooxygenase-2 and other enzymes for the production of lipidmetabolites capable of stabilizing and activating PPARδ." (PMID 18551186, 2008). "Relevant to cancer is the presumed role of PPARδ ininflammation and NF-κB regulation." (PMID 18528523, 2008). "However, the role of PPARδ incolon cancer is still unclear, as there are data suggesting that it either inhibitsor promotes colon carcinogenesis." (PMID 18483618, 2008). "At this stage, thejury should be considered out on the role of PPARδ in cancer." (PMID 18528523, 2008). "Another study showedthat anticancer effects were associated with reductions in tubulin levels (avalidated cancer-related target), but this was not mediated by PPARγ, PPARδ, or the proteasome." (PMID 18779871, 2008). "Peroxisome proliferator-activated receptor δ may have a supporting role in tumorigenesis, and the close association between PPARδ expression and malignant morphology of CRC cells suggests a pivotal role in cancer tissue." (PMID 16969348, 2006). "In contrast, PPARδ-negative cancer cells had morphological features associated with a low malignant phenotype, such as an oval and small nucleus without a distinct nucleolus, and preserved cellular polarity." (PMID 16969348, 2006). "However, the immunosuppressive function of IL10+ IgD- CD38+ Bregs could be blocked, and cancer immunotherapy enhanced, by using PPARδ inhibitors." (PMID 38826800, 2024). "Gaining detailed knowledge of PPARδ’s actions in CTLs and other immune cell types will help elucidate the molecular mechanisms by which CTLs eradicate cancer cells and aid the development of new therapeutic strategies, possibly both for cancer prevention/interception and treatment." (PMID 39292167, 2024). "In addition to PPARγ, PPARδ could also act as an essential mediator for 83b1 to exert anti-cancer effects on human esophageal cancers by down-regulating cancer-related genes and molecules." (PMID 37025484, 2023). "PPARδ, another isotype, is highly expressed in tissues such as the lung, kidney, and heart, and can regulate the expression of target genes involved in cardiovascular diseases, cancers, and gastrointestinal diseases in combination with progression and treatment at the DNA-binding domain." (PMID 37025484, 2023). "For example, panobinostat, vorinostat, and romidepsin inhibit glycolysis in cancer cells by enhancing the oxidative metabolism (potentiating the expression of peroxisome proliferator-activated receptor gamma coactivator 1-alpha (PGC1α) and peroxisome proliferator-activated receptor beta (PPARδ))." (PMID 37296584, 2023). "However, the role of PPARD in the development of GC and other types of cancer is still elusive." (PMID 35163565, 2022). "Thus, the role of PPARδ in skin tumorigenesis remains controversial, and the opposing views might owe to the use of different cancer cell lines, patient tissues, cancer staging and progression." (PMID 34298981, 2021). "Therefore, PPARδ agonists may be useful in treating metabolic disorders, while antagonists may reduce inflammation-related disorders and slow down cancer progression." (PMID 35010191, 2021). "However, the opposite was observedby another group, which found that regular NSAIDs use reduced the risk ofcolorectal cancer, but none of the polymorphic genes studied, including PPARδ,modified their protective effect." (PMID 18528523, 2008). "Therefore, additionalanalyses are necessary to define the PPARδ functions in cancer." (PMID 18584037, 2008). "Indeed,tissue microarray analysis of invasivebreast cancers indicated that PPARδ is strongly expressed (“+3”) in 52% of 164 samples, and thus may have value as a prognosticmarker and therapeutic target." (PMID 18566686, 2008). "However,further investigation is required to certify the regulation of PPARδ expression in cancer." (PMID 18584037, 2008).
cancer (continued). "Specifically, genes like PPARD, RPL3, and STAT1, which overlapped in both our epigenomic and transcriptomic analyses, are highly interconnected across AIDs and cancer." (PMID 40429780, 2025). "In summary, PPARδ integrates microenvironmental signals to reprogram PDAC cell metabolism via the MYC/PGC1A axis, thereby promoting cancer cell invasiveness and in vivo metastasis in PDAC." (PMID 40607925, 2025). "Thus, PPARδ may serve as a valuable target for developing future cancer immunotherapies." (PMID 39292167, 2024). "In summary, this study was the first to comprehensively analyze the expression patterns of PPARA, PPARD and PPARG in multiple cancers including in STAD." (PMID 38529307, 2024). "PPARA, PPARD and PPARG were more abnormally expressed in STAD samples and cell lines when compared to most of 32 type cancers in TCGA." (PMID 38529307, 2024). "PGE2 contributes to the development and progression of many cancers by activating the membrane receptors EP (including EP1, EP2, EP3, and EP4 receptors) and the nuclear receptor PPARδ of target cells." (PMID 38764576, 2024). "The expression profiles of three PPAR genes (PPARA, PPARD and PPARG) were downloaded from The Cancer Genome Atlas (TCGA) dataset to analyze their expression patterns across pan-cancer." (PMID 38529307, 2024). "Expression of STC1 is up‐regulated during the metastasis process induced by overexpression of PPARD in cancer cells, indicating a pro‐metastasis effect of STC1 on cancer." (PMID 32468698, 2020). "In this study, we analyzed the expression signatures of PPARA, PPARD, PPARG, PPARGC1AA, and PPARGC1B in pan-cancer." (PMID 33029111, 2020). "The expression patterns of PPARA (p < 0.001), PPARD (p < 0.001), PPARG (p < 0.001), PPARGC1A (p < 0.001), and PPARGC1B (p < 0.001) varied in 6 immune subtypes in pan-cancers." (PMID 33029111, 2020). "From the forest plot, we found that PPARD and PPARG were of pan-cancer significance with HR > 1 in most cancer types." (PMID 33029111, 2020). "Clinical trials on selected PPARδ agonists have assessed both metabolic and vascular outcomes and no severe side effects have been reported to date, except for GW1516, which induced cancer in several organs in rodents." (PMID 30060458, 2018). "PPARδ activation stimulates VEGF production in mice,which at least in part had an autocrine prosurvival effect on cancer cells." (PMID 18551186, 2008). "No changes were observed in PPARγ mRNA expression while the expression of PPARδ, retinoid-activated receptors and COX-2 were significantly increased in cancer tissues compared to normal colon mucosa (P ≤ 0.001)." (PMID 17767717, 2007). "Given the importance of maintaining stemness in cancer, we hypothesize that during EMT, PPARδ emerges as a crucial driver of stemness, making CSCs less dependent on mitochondrial metabolism." (PMID 40607925, 2025). "Notably, PPARD was reported to bind PPREs in the promoters of ANGPTL4 and PDK4 in cancer cells, leading to their upregulation." (PMID 40652248, 2025). "In this study, we now conclusively demonstrate that PPARδ (peroxisome proliferator–activated receptor δ) activation precedes and facilitates the acquisition of a prometastatic state in PDAC cancer (stem) cells, characterized by metabolic plasticity and epithelial-to-mesenchymal (EMT)-like features." (PMID 40607925, 2025). "The expression of PPARA, PPARD and PPARG in a total of 32 types of cancers was determined." (PMID 38529307, 2024). "Similar to the observations in mice, human CD19+CD24hiIgDlo/−CD38lo and CD19+CD24hiIgDlo/−CD38hi Bregs were also found to express a higher level of PPARδ than human CD19+CD24loIgDhi mature B cells, and frequencies of both Breg subsets were increased in cancer patients compared to healthy subjects." (PMID 37291146, 2023). "In addition, by qPCR and RNA-seq we identified several cancer-related genes that regulated by AS of APEX1, which included AXIN1, GCNT2, SMAD3, CTBP2, PPARD, and FBXW11." (PMID 35780128, 2022).
cancer (continued). "Unlike in many cancer systems, we found that PPARD-overexpressing GC was not primarily dependent on aerobic glycolysis for fuel." (PMID 35163565, 2022). "Peroxisome proliferator-activated receptor delta (PPARD) is a nuclear receptor known to play an essential role in regulation of cell metabolism, cell proliferation, inflammation, and tumorigenesis in normal and cancer cells." (PMID 35163565, 2022). "Activation of PPARδ via ligand binding releases the loop, which favors the transcription of VEGFA, and might sustain cancer growth." (PMID 34298981, 2021). "Further investigations are required to figure out the potentials of PPARs and their coactivators as drug targets for cancer, which makes our study even more important in the contribution to the expression signature analysis of PPARA, PPARD, PPARG, PPARGC1A, and PPARGC1B." (PMID 33029111, 2020). "Functions of the remaining genes - including CSNK1E, FOSL1, PPP2R1A, and PPARD – are widely reported as being relevant to cancer (if not specifically NSCLC) biology." (PMID 33027769, 2020). "Finally, miR-486-5p also promote the expression of five genes with promoting cancer roles: KDM4C, PPARD, KLF4, STAT3, and TCF7l2." (PMID 33227890, 2020). "Despite the apparent importance of PPARδ in cancer biology, there are presently no PPARδ antagonists available for clinical use." (PMID 27270614, 2016). "It was of interest that a cancer tissue often contained both PPARδ-positive and -negative areas, with maintenance of these respective, specific morphological features." (PMID 16969348, 2006). "During the current study, we found that PPARδ-expressing cancer cells often presented such nuclear features, whereas PPARδ-negative cells did not." (PMID 16969348, 2006). "We found PPARD, which had the highest RSS and has been reported to accelerate CRC progression, to be activated in C4 cells, suggesting that it might drive the invasive properties of cancer cells." (PMID 36209225, 2022). "To date, the role of PPARδ in cancer metastasis is not clear and is highly debated." (PMID 33637678, 2021). "However, the knockdown of p65 abolished the increase of PPARδ proteins-induced by HBXIP, indicating that HBXIP boosts the expression of PPARδ in a NF-κB-dependent manner in cancer cells." (PMID 29416623, 2018). "It is not entirely clear why PPARδ should be expressed by aggressive cancers." (PMID 27270614, 2016). "Data from noncolonic cell lines and tissues alsosupport a role for PPARδ in cancer." (PMID 18528523, 2008). "Moreover, this pattern persisted even when PPARδ-positive and -negative cells were aligned next to each other within a single cancer nest or gland and was present in the majority of CRC cases." (PMID 16969348, 2006). "Interestingly, the cancer tissue often contained both PPARδ-positive and -negative areas, each retaining their respective specific morphological features." (PMID 16969348, 2006). "Moreover, this rule was maintained even when PPARδ-positive and -negative cells were aligned next to each other within a single cancer nest or gland." (PMID 16969348, 2006). "However, PPARD was not validated as candidate cancer gene in these analyses." (PMID 24391853, 2013). "The results clearly demonstrate that low expression of ACOX2 in cancer cells significantly inhibits the expression of PPARA, but not PPARD and PPARG." (PMID 33414412, 2021).
metabolic disorders (52 papers, 2007 to 2025). "We have previously shown that obese subjects at risk had reduced PBMC gene expression of PPARD compared with metabolically healthy obese and control subjects, and PPARD activation improves multiple metabolic disorders (especially blood lipids) in obese subjects." (PMID 27482295, 2016). "Natural PPAR ligands in Vietnamese medicinal fungi and plants showed strong PPARδ activity, indicating potential for metabolic disorder prevention." (PMID 40421417, 2025). "GW501516, also known by the name of cardarine, is a synthetic peroxisome-proliferator-activated receptor delta (PPR-δ) agonist agent developed for applications in the treatment of metabolic disorders and cardiovascular diseases." (PMID 38794285, 2024). "PPARδ contributes to anti-inflammation and anti-apoptosis effects and suppresses cellular migration in metabolic diseases by inhibiting IL1β." (PMID 33318871, 2021). "We were curious that PPARδ activation can induce modification of the mitochondrial respiration chain to protect cellular against metabolic disorder induced by EtOH." (PMID 32760285, 2020). "Peroxisome proliferator-activated receptor δ (PPARδ) belongs to the nuclear receptor family and is involved in metabolic diseases." (PMID 30814493, 2019). "Generally, AMPK is involved in decreasing inflammation as well as ameliorating the symptoms of metabolic diseases, which is also regulated by PPARδ." (PMID 30622619, 2018). "All these studies suggest a protective effect of PPARδ activation in thecardiovascular complications induced by metabolic disorders." (PMID 19325917, 2009). "PPARδ activators have been proposed for thetreatment of metabolic disease and are under clinical trial." (PMID 18584037, 2008). "On the basis of the literature, one can think that several therapeuticapproaches using PPARδ agonists may be possible to treat vascular and cardiacpathological states, especially those in which inflammation, fibrosis, andlipid metabolic disorders are involved." (PMID 19325917, 2009). "PPARδ activatorshave been proposed for the treatment of metabolic disease." (PMID 18584037, 2008). "Here, we have summarized the functional activation of the PPARδ in co-ordination with the Wnt/β-catenin pathway during the regulation of several aspects of embryonic development, stem cell regulation and maintenance, as well as during the progression of several metabolic disorders." (PMID 33673357, 2021). "Thus, it is proposed that activators of PPARδ may have therapeutic utility in the treatment of metabolic disease." (PMID 22479450, 2012). "As shown by microarray analyses, mRNA levels of the Wnt/β‐catenin signalling target genes related to metabolic diseases, including TCF7L2, WISP‐1, IGF‐1 and PPARδ, were lower in the visceral adipose tissues from patients with T2DM than in tissues from non‐diabetic subjects." (PMID 35384342, 2022). "Since acute 5% EtOH consumption reduces metabolic regulation factors related to PPARδ including pAMPK, CPT1, and GLUT4, we speculated that PPARδ can directly or indirectly involved in metabolic disorder by chronic alcohol consumption." (PMID 32760285, 2020).
cardiovascular disease (23 papers, 2005 to 2025). "The effect of PPARδ ligands on catalase expression may mediate many of the functions of PPARδ, implicating it as a key target for therapeutic intervention in ROS-related cardiovascular disorders such as hypertrophy." (PMID 34439471, 2021). "Currently, no PPARδ agonists are clinically approved at the present moment, but they may be beneficial for the treatment of cardiovascular disorders and improve overall cardiovascular risk assessment." (PMID 19696948, 2009).